TAS2R40 (taste 2 receptor member 40)
Description:
Gustducin-coupled receptor implicated in the perception of bitter compounds in the oral cavity and the gastrointestinal tract. Signals through PLCB2 and the calcium-regulated cation channel TRPM5.
Synonyms: T2R40; T2R58; GPR60
Tractability: Antibody: its Gene Ontology location is reachable by antibodies, with high confidence; UniProt predicts a signal peptide or a membrane-spanning region. PROTAC: a small molecule that binds it is known.
Target class: Membrane receptor; Taste receptor (taste family GPCR); Taste family G protein-coupled receptor
Gene: Protein-coding gene on chromosome 7 (143,222,037 to 143,223,079, forward strand). Ensembl gene ENSG00000221937.
Subcellular location: Membrane
Pathways (Reactome):
Signal Transduction: Class C/3 (Metabotropic glutamate/pheromone receptors); G alpha (i) signalling events
Sensory Perception: Sensory perception of sweet, bitter, and umami (glutamate) taste
Gene Ontology:
Molecular function: bitter taste receptor activity; G protein-coupled receptor activity
Biological process: detection of chemical stimulus involved in sensory perception of bitter taste; G protein-coupled receptor signaling pathway; sensory perception of taste
Cellular component: membrane; plasma membrane
Genetic constraint (gnomAD): Loss-of-function variants: 14 observed, 17.47 expected, observed/expected ratio (o/e) 0.8, 90% interval 0.53 to 1.25. The upper end of that interval is the gene's LOEUF score, 1.25, which puts it in group 5 of 6, group 1 being the genes least tolerant of losing a copy. Missense variants: 350 observed, 407.5 expected, observed/expected ratio (o/e) 0.86, 90% interval 0.79 to 0.94. Synonymous variants: 152 observed, 158.11 expected, observed/expected ratio (o/e) 0.96, 90% interval 0.84 to 1.1.
Homologues: Orthologues: chimpanzee TAS2R40 (99% identical), macaque TAS2R40 (96% identical), dog TAS2R40 (72% identical), mouse Tas2r144 (65% identical), rabbit TAS2R40 (64% identical), rat Tas2r144 (63% identical), guinea pig TAS2R40 (63% identical), pig TAS2R40 (52% identical), tropical clawed frog tas2r7 (29% identical), tropical clawed frog t2r2 (27% identical), tropical clawed frog tas2r4 (27% identical), tropical clawed frog t2r10 (27% identical), and 10 more. Paralogues in human: TAS2R39 (56% identical), TAS2R9 (31% identical), TAS2R7 (29% identical), TAS2R8 (28% identical), TAS2R60 (27% identical), TAS2R1 (27% identical), TAS2R41 (26% identical), TAS2R3 (25% identical), TAS2R4 (25% identical), TAS2R14 (25% identical), TAS2R10 (25% identical), TAS2R13 (24% identical), and 11 more.